CD47 (CD47 molecule)
Diseases named in the same sentence as CD47 in open-access papers (continued):
Sharing a sentence is not in itself a finding about the gene and the disease.
tumor (continued). "Because tumor cells potentially utilize the CD47 pathway to evade both innate and adaptive components of immune surveillance, therapeutic blockade of this pathway may activate antitumor immunity and improve cancer therapy." (PMID 30133535, 2018). "Tumor-initiating cells are characterized by high expression of CD47." (PMID 29541403, 2018). "In a recent study, anti-CD47 and anti-PD-L1 monotherapies were used against tumor mice models." (PMID 30399174, 2018). "Preclinical studies have demonstrated that the strategy of using monoclonal antibody (mAb) specific for CD47 could inhibit growth and metastasis of tumor cells for cancer treatment." (PMID 28290053, 2018). "We found that soluble mSIRPαext polypeptide, a recombinant extracellular fragment of the mouse SIRPα (mSIRPαext), could promote M1 polarization of macrophages and increase their phagocytic activity to L1210 tumor cells in a CD47-dependent way." (PMID 30105024, 2018). "In conclusion, the CD47 blockade therapy, which can reeducate M2 macrophages by increasing their phagocytosis ability, might be an attractive target for tumor immunotherapy for EC." (PMID 30525058, 2018). "CD47 is overexpressed on tumor cells and considered as a marker for cancer prognosis." (PMID 30533489, 2018). "Because CD47 is also expressed at high levels on normal healthy cells, such as platelets and erythrocytes, these molecules have the potential to induce phagocytosis of non-tumor cells and result in toxicity." (PMID 30133535, 2018). "Besides, the in vivo experiment suggested that there were smaller tumor sizes and increased TAMs which dominantly consisted of M1 macrophages in the CD47-knockdown group, indicating that these macrophages played an important role in eliminating EC cells." (PMID 30525058, 2018). "Besides, interruption of the ligation of CD47 and SIRPα promotes the tumor cells to be phagocytosed by macrophages in various malignancies." (PMID 30525058, 2018). "There has been a controversy on the mechanism of anti-tumor effects induced by anti-CD47 mAbs." (PMID 28380460, 2017). "In order to determine whether anti-CD47 antibody was effective against tumor growth in a setting more similar to the clinic, treatment was initiated 4 weeks after implantation, a time point where tumor was clearly evident in rats by MRI." (PMID 28076333, 2017). "In this study, we sought to assess whether blockade of CD47 by SIRPαFc could increase phagocytosis of tumor cells by six phenotypically distinct macrophage subsets derived from human monocytes." (PMID 29084248, 2017). "Intra-tumor injection of CD47-CAR-T cells increases the safety of these cells." (PMID 29065481, 2017). "However, MYC inactivation in tumors due to enforced CD47 or PD-L1 expression leads to suppressed immune responses and continued tumor growth." (PMID 28757546, 2017). "Interestingly, CD31 immunostainings and μCT analysis of tumor angiography highlighted that the angiostatic properties of TAX2 peptide targeting TSP-1:CD47 interaction are preserved in such a pro-vascular microenvironment." (PMID 28794454, 2017). "CD47 could interact with its counter-receptor SIRPα on macrophages and other myeloid cells to inhibit tumor cell phagocytosis and trigger immune evasion." (PMID 28469973, 2017). "In addition, CD47 signaling has been shown to play a key role in maintenance of tumor initiating or cancer stem cells." (PMID 29065481, 2017). "We hypothesized that the high affinity for CD33 of the licMABs would facilitate preferred tumor antigen-binding over healthy CD47-expressing cells." (PMID 28061465, 2017). "Second, in xenograft models, only human tumor cells express human CD47." (PMID 28077173, 2017). "Accumulating evidence suggests that CD47 expression on human solid tumor cells and especially CSCs is a common mechanism through which these cells protect themselves from phagocytosis, allowing tumor cell proliferation and metastasis." (PMID 28484448, 2017).
tumor (continued). "Similarly, CD47 blockade was reported to enhance tumor cell phagocytosis by macrophages, reduce tumor burden, and increase survival in glioblastoma, gastric cancer, and pancreatic neuroendocrine tumor xenograft models." (PMID 28100392, 2017). "Indeed, adaptive immune response, particularly that mediated by T cells, plays an important role in mouse anti-CD47 blockade-induced tumor control." (PMID 28077173, 2017). "We also investigated whether NK cells could mediate tumor elimination by anti-CD47 antibody in vitro." (PMID 28484448, 2017). "In addition, the CD133+ tumor initiating cells expressed a high level of CD47, and anti-CD47 mAb treatment was able to trigger the phagocytosis of this cell population." (PMID 28380460, 2017). "Indeed, CD47 blocking antibodies have been found to decrease primary tumor size and/or metastasis in various pre-clinical models." (PMID 28077173, 2017). "In addition to CD47 targeting, tumor immunosuppression can be overcome through targeting indoleamine 2,3-dioxygenase (IDO)." (PMID 29065490, 2017). "By neutralizing CD47, tumor cells could be efficiently killed effector cells mediated by their Fc portion." (PMID 28469973, 2017). "For instance, recently it was demonstrated that the blocking of programmed death-ligand in tumour cells to recruit the adaptive immune system is important to potentiate the recruitment of the innate immune system (through the disruption of CD47–SIRPα interaction) to target cancer cells." (PMID 28378740, 2017). "In addition, CD47 signaling blockade activates both, an antitumor T lymphocyte immune response and T cell-mediated killing of CD47-expressing tumor cells." (PMID 29312320, 2017). "Furthermore, blocking CD47 signaling promotes engulfment of tumor cells by macrophages in vitro and inhibits xenograft tumor growth, prevents metastases and prolongs survival in vivo." (PMID 29156578, 2017). "The results indicate that CD47 blocking immunotherapy might be a promising postsurgical treatment for GBM and that targeting CD47 has the potential to eliminate tumor cells driving recurrence in GBM." (PMID 28076333, 2017). "In parallel, we measured CD47 levels of expression in the tumours after dissociation of the cells." (PMID 28378740, 2017). "This unique feature could put human tumor cells under CD47-SIRPα control more so in NSG mice than in other strains of mouse, making them more susceptible to signaling blockade." (PMID 28077173, 2017). "In addition, intratumoral injection of CD47-CAR-T cells significantly decreased BxPC3 xenograft tumor growth using NSG mice." (PMID 29065481, 2017). "Membrane proteins, including MUC18, CA199 and CD47, could enhance cell adhesion, therefore show highly potential as tumor progression markers." (PMID 28841878, 2017). "Blockade of the CD47-SIRPα pathway using anti-CD47 antibodies, SIRPαFc or by CD47 siRNA knockdown have been shown to increase phagocytosis of tumor cells by in vitro generated M1 and M2 macrophages, which represent two extremes along a continuum of macrophage activation." (PMID 29084248, 2017). "CD47, an immune evasion marker on the surface of many solid cancers, may represent a more relevant tumor immunosuppressive target." (PMID 29065490, 2017). "The blockade of the CD47-SIRPα signaling pathway has recently been investigated as a therapeutic tool, and several approaches to disrupt the CD47-SIRPα axis, including mAbs against CD47 and CD47-antagonists, have been shown to stimulate clearance of tumor cells by phagocytosis." (PMID 28061465, 2017). "To investigate whether NK cells could mediate tumor elimination by anti-CD47 antibody in vitro, we utilized human NK cells (CD3−CD56+CD7+) as effectors." (PMID 28484448, 2017). "The results indicate that anti-CD47 therapy effectively enhanced treatment of recurrent tumors in the context of postsurgical tumor resection and thus might potentially improve overall survival of patients with GBM." (PMID 28076333, 2017).
tumor (continued). "Expected beneficial effects of this immunotherapy involve the inhibition of tumor angiogenesis and invasion, decrease of tumor-induced macrophage apoptosis and functional impairment, and depletion of CD47-expressing cancer stem cells that are key contributors to tumor relapse and chemoresistance." (PMID 28714932, 2017). "CD47 is a glycoprotein of the immunoglobulin superfamily that is often overexpressed in different types of hematological and solid cancer tumors and plays important role in blocking phagocytosis, increased tumor survival, metastasis and angiogenesis." (PMID 29065481, 2017). "Thus, our studies establish licMABs as a possible therapeutic approach to locally deliver the benefit of CD47-SIRPα blockade to tumor cells." (PMID 28061465, 2017). "We also compared tumor growth and angiogenesis between WT and CD47−/− tumor cells." (PMID 27283989, 2017). "The UPR-mediated upregulation of CD47 expression then may result in tumor expansion and insensitivity to anti-cancer therapies." (PMID 28815041, 2017). "Therefore, stimulation of tumor cell phagocytosis by blocking the CD47-SIRPα axis enhances antigen-presentation and ultimately leads to increased tumor elimination." (PMID 28061465, 2017). "CC-90002 selectively binds to CD47 expressed on tumor cells, blocks CD47 interaction with signal regulatory protein alpha (SIRPa), a protein expressed on phagocytic cells, which prevents CD47/SIRPa-mediated signaling and abrogates the CD47/SIRPa-mediated inhibition of phagocytosis." (PMID 29312320, 2017). "As CD47 is a negative regulator of phagocytosis, the hypothesis that blocking CD47 could promote tumor cell elimination emerged." (PMID 28234345, 2017). "Some people argue that the Fc fragment might be participating in the anti-tumor effect of anti-CD47 mAb." (PMID 28380460, 2017). "The hypothesis that blocking CD47-SIRPα interactions would restore phagocytosis of tumor cells has been widely validated in primary human xenograft models treated with commercial and clinically developed anti-CD47 antibodies." (PMID 29387053, 2017). "Thus, our data illustrated a novel PEDF-mediated signaling involving PNPLA2 up-regulation on macrophages to induce M1 polarization and, CD47 down-regulation on tumor cells which in collaboration with ATP5B elevation on macrophages leads to phagocytosis." (PMID 28403150, 2017). "Interestingly, stimulation through TLR-3, -4, and -7 has previously been reported to synergize with CD47 blockade on tumor cells by increasing secretion and cell-surface exposure of calreticulin on macrophages in a Btk-dependent manner." (PMID 29084248, 2017). "We further tested whether anti-human CD47 antibody can increase the number of macrophages in the tumor tissues in the xenotransplant models." (PMID 28484448, 2017). "Our current study shows that inhibition using anti-CD47 mAb, which enables macrophages to eliminate tumor cells, could also induce robust phagocytosis of the TICs." (PMID 28380460, 2017). "Tumor cells expressed higher levels of CD47 than normal cells." (PMID 28484448, 2017). "In addition, CD47-CAR-T cells significantly blocked BxPC3 pancreatic xenograft tumor growth after intratumoral injection into NSG mice." (PMID 29065481, 2017). "Moreover, loss of CD47 was associated with increased CD68+ and CD163+ macrophage infiltration, which correlated with reduced tumor grade and lymph node metastasis." (PMID 28815041, 2017). "Thus, anti-CD47 antibodies are able to stimulate phagocytosis being effective after confirmation of CD47 expression on tumor cells." (PMID 28470464, 2017). "The complete mechanism of dual effects on cell survival behind CD47 blockade is not completely understood, but CD47 may differentially regulate autophagy in normal and tumor tissue through cross-talk with the UPR pathway." (PMID 28815041, 2017).
tumor (continued). "Hence, engineering macrophages with rewired CD47 signaling, together with monoclonal antibodies to specifically target tumor cells, can lead to a revolutionary development of next-generation immunotherapy." (PMID 28883531, 2017). "This indicated that NK cell was a potential contributor to tumor suppression in anti-CD47 antibody antitumor, and the antitumor effect obtained in the xenograft model may in part be mediated by mouse NK cells." (PMID 28484448, 2017). "MYC has been shown to directly regulate the expression of the tumor cell surface immune checkpoint protein cluster of differentiation 47 (CD47) and programmed death-ligand 1 (PD-L1), which mediate “don’t eat me” and “don’t find me” signals, respectively, following MYC binding to their promoters." (PMID 28757546, 2017). "Thus, all together, these results provide a potential mechanism for the enhanced anti-tumor activity observed with blockade of CD47-SIRPa in the context of surgical debulking." (PMID 28076333, 2017). "The MYC regulates the expression of two immune checkpoint proteins on the tumor cell surface, the innate immune regulator, CD47 (Cluster of Differentiation 47) and the adaptive immune checkpoint, PD-L1 (programmed death-ligand 1), thereby initiates and maintains the tumorigenesis." (PMID 28278192, 2017). "To locally interfere with the CD47-SIRPα axis at the tumor site, we generated the so-called local inhibitory checkpoint monoclonal antibodies (licMABs), which consist of the endogenous SIRPα V-like domain linked to a mAb targeting CD33, a validated target antigen in AML." (PMID 28061465, 2017). "Studies performed with experimental models of solid tumors including GBM as well as some hematopoietic cancers have shown that blocking the interaction between CD47 and SIRPα with anti-CD47 monoclonal antibodies (mAbs) promotes phagocytosis in vitro and inhibits tumor growth in vivo." (PMID 28076333, 2017). "We then examined whether SIRPα Shp2-iSNAP can also promote the phagocytic power of primary macrophages against tumor cells expressing CD47." (PMID 28883531, 2017). "CD47 is also highly expressed in cancer stem cells, the most aggressive type of tumor cells." (PMID 29065481, 2017). "The differential regulation of CD47 expression by GRP78 also may explain why CD47 blockade in preclinical models resulted in tumor sensitization to ionizing radiation, but protected soft tissues and bone marrow from toxicity." (PMID 28815041, 2017). "In patients with lung metastasis, the number of circulating tumor cells (CTC) with the phenotype EPCAM(+)CD44(+)CD47(+)MET(+) were associated with poor overall survival and increased metastasis and CD47 was a marker associated with the fraction of metastasis-initiating cells within the pool of CTCs." (PMID 26941482, 2016). "In addition to antibodies, targeting tumor CD47 using antisense strategies is another promising approach to inhibit CD47 function." (PMID 27671753, 2016). "Elimination of tumor cells by anti-CD47 antibodies may occur through a variety of mechanisms which include both phagocytic and non-phagocytic tumor cell killing by neutrophils and NK cells." (PMID 27092773, 2016). "Blocking CD47/SIRPα interaction could induce phagocytosis and enable DCs to cross-present tumor antigens through MHC class I molecules, which further activates CD8+ T cells that are specific for tumor antigens." (PMID 27863402, 2016). "Recently, CD47 has been identified as a “don’t eat me” signal on tumor cells." (PMID 27092773, 2016). "Of note, pretreatment of tumor cells resulted in an equal phagocytosis induction as when adding the antibody directly to the macrophage-tumor cell mix, which is explained by CD47-Sirpα disruption on GBM, whereas pretreatment of macrophages alone was not correlated to higher tumor-cell phagocytosis." (PMID 27092773, 2016).
tumor (continued). "Furthermore, it has been shown that CD47/SIRPα and SIRPα signaling negatively regulate antibody-dependent elimination of tumor cells, which supports the idea of targeting CD47/SIRPα interaction to enhance the clinical effects of cancer therapeutic antibodies." (PMID 27671753, 2016). "Strong co-staining of both proteins from sequential sections could be detected in tumor samples with high CD47 expression, while minimal staining of Cdc42 was detected in those with low CD47 expression." (PMID 27411490, 2016). "CD47 is widely expressed on all cell types although tumor cells have increased levels of CD47 expression compared to normal cells, which turns into a mechanism by which tumor cells can evade phagocytosis." (PMID 27671753, 2016). "This circumstance might be additionally favorable for GBM patients with high proportions of M2 macrophages within their tumors, as anti-CD47 treatment promotes these macrophages towards tumor phagocytosis." (PMID 27092773, 2016). "The dual role of CD47 in promoting inflammation through neutrophil migration and recognition of self through blocking phagocytosis in macrophages plays a role in the development of cancer and later in tumor immune evasion." (PMID 26941482, 2016). "In vivo, CD47-specific shRNA significantly reduced tumor growth and metastasis." (PMID 27411490, 2016). "All tumor cell lines as well as the neural stem cell line expressed CD47 at a high level." (PMID 27092773, 2016). "Our data support the usage of PPRHs to diminish CD47/SIRPα interaction by decreasing the expression of both molecules thus resulting in an enhanced killing of tumor cells by macrophages, which might translate into beneficial effects in cancer therapy." (PMID 27671753, 2016). "The interactions of CD47-SIRPα form a barrier for antibody-mediated tumor cell destruction." (PMID 26988913, 2016). "There were reports that circulating tumor cells (CTCs) overexpressed CD47." (PMID 26840024, 2016). "Also, the HIF-1 stimulates production of CD47 in tumor cells, a cell surface protein that enables tumor cells to avoid destruction by macrophages." (PMID 27630452, 2016). "CD47 expression on tumor cell membranes and subsequent binding to signal-regulatory protein alpha (SIRPα) on macrophages lead to a signal cascade within the macrophages that inhibits macrophage-mediated tumor cell phagocytosis." (PMID 27092773, 2016). "By decreasing the level of CD47 in tumor cells, 60 % of MCF-7 cells were killed by macrophages." (PMID 27671753, 2016). "Knockdown of SIRPα (and therefore mimicking CD47–SIRPα disruption) has also recently been shown to induce migration of macrophages towards tumor cells, strengthen macrophage survival and propagate a proinflammatory cytokine response via NF-κB signaling, which is consistent with an M1-phenotype." (PMID 27092773, 2016). "Furthermore, to what extent M1 versus M2 macrophage polarization affects phagocytosis of tumor cells in the setting of anti-CD47 treatment has yet to be evaluated." (PMID 27092773, 2016). "However, mice treated with the CD47-derived peptide exhibited a substantial tumor necrosis at day 20 after tumor challenge." (PMID 26046793, 2015). "In this work, we focus on the tumour cells characterised by CD44, CD47 and MET mutations." (PMID 25978366, 2015). "Healthy cells and tumor cells display the “don’t eat me” CD47 molecule." (PMID 25688334, 2015). "Apart from TSP-1-related direct modulation of cancer cell behavior through interactions with membrane receptors, the TSP-1/CD47/SIRPα axis is also strongly implicated in controlling tumor immunity, with both positive and negative roles." (PMID 26578962, 2015). "However, macrophages fail to phagocytose tumor cells due most likely to the high expression of CD47, which inhibits tumor cell phagocytosis." (PMID 26462157, 2015).